ALK (ALK receptor tyrosine kinase)
Diseases named in the same sentence as ALK in open-access papers (continued):
Sharing a sentence is not in itself a finding about the gene and the disease.
lung cancer (continued). "Treatment of ALK rearranged positive lung cancer requires sequential use of first‐, second‐, and third‐generation ALK inhibitors, but the sensitivity of these drugs differs for each resistance, and individualized treatment will be required for patients." (PMID 31943796, 2020). "Accurate detection of anaplastic lymphoma kinase (ALK) rearrangement is the prerequisite for anti‐ALK therapy for the patient with non‐small cell lung cancer (NSCLC)." (PMID 32543087, 2020). "Approximately 80% of lung cancers is associated with NSCLC driven by molecular EGFR mutations and ALK receptor tyrosine kinase translocations." (PMID 32913247, 2020). "In the tissue FISH database of the Clinical Cytogenetics Laboratory during the time interval of this study, 384 lung cancer patients were tested two or more times for ALK FISH." (PMID 32674491, 2020). "Currently, the choice of first‐line treatment for advanced non‐small cell lung cancer (NSCLC) depends on the presence of genetic aberrations, such as mutations of epidermal growth factor receptor (EGFR) and translocations of anaplastic lymphoma kinase (ALK)." (PMID 31808285, 2020). "ALK inhibitors in lung cancer can be openly considered for use in Indonesian patients to improve the outcome of this subset of patients." (PMID 33425389, 2020). "Another convincing example has been reported with the L1198F mutation of ALK, which confers resistance to lorlatinib but restores sensitivity to crizotinib in ALK rearranged lung cancers." (PMID 32272741, 2020). "It has been reported that programmed death-ligand 1 (PD-L1) expression is high in ALK-positive lung cancer." (PMID 32283823, 2020). "Several ALK inhibitors can effectively suppress the oncogenic activity of ALK rearrangement and provide a better outcome; hence, they have emerged as important front-line therapies in advanced ALK-positive lung cancer patients." (PMID 33273548, 2020). "Crizotinib and lorlatinib both target ALK and have significant inhibitory effects on ALK‐positive lung cancer cells, however, lorlatinib is better at crossing the blood brain barrier (BBB), improving intracranial disease control." (PMID 32347012, 2020). "We also detected the atypical lung cancer mutations BRAF (p.G469V) and ALK (p.R1275Q), whose clinical significance should be further evaluated." (PMID 32441866, 2020). "In lung cancer, patients with mutation of common driver genes (such as EGFR and ALK) can benefit from targeted therapy." (PMID 33537237, 2020). "Here, the authors elucidate the dynamics of developing resistance to ALK inhibitors in an ALK+ lung cancer cell line showing that resistance originates from drug-specific tolerant cancer cells and it develops as a gradual adaptation." (PMID 32409712, 2020). "The aim of our study is to explore the validity of a Lung-molGPA index in an ALK-positive lung cancer cohort with BM, and propose a new prognostic scoring system which can easily be applied in clinical practice." (PMID 32640547, 2020). "Crizotinib, the first ALK inhibitor to be introduced for the treatment of lung cancer in 2011, has rapidly become the gold standard for this type of cancer." (PMID 31945065, 2020). "This multicenter study retrospectively investigated later-line, real-world use of lorlatinib in patients with advanced ALK- or ROS1-positive lung cancer." (PMID 33171712, 2020). "Among the 54 established PDX models, 12 were developed from FGFR-driven tumours resistant to erdafitinib, 9 from EGFR-mutant osimertinib resistant tumours and 4 from ALK-rearranged lung cancers resistant to lorlatinib." (PMID 32964129, 2020). "These involve genes like MUC16 (CA125) whose levels relate to different stages of NSCLC, and PTK7 that is associated with lymph node metastasis as well as ALK and EGFR mutations in lung cancer." (PMID 33255394, 2020).
lung cancer (continued). "Currently, all clinical trials of first-line ICIs, either single- or dual-agent, have excluded EGFR-mutant and ALK-rearranged lung cancers but included patients with RET-rearranged lung cancers." (PMID 32295619, 2020). "Current guidelines recommend that all patients with adenocarcinomas be tested for routine biomarkers, including EGFR mutations, ALK rearrangement, and ROS1 rearrangement, because FDA-approved agents for lung cancer are available for these biomarkers." (PMID 33005033, 2020). "Histologic transformation from non-small cell to small cell lung cancer has been reported as a resistance mechanism to targeted therapy in EGFR-mutant and ALK fusion-positive lung cancers." (PMID 32802958, 2020). "Anaplastic lymphoma kinase (ALK) fusion genes are found in 3%–5% of non‐small cell lung cancers (NSCLCs)." (PMID 31943796, 2020). "In the cohort of young patients with LUAD from our center, we observed obvious heterogeneity between our cohort and the population of lung cancer worldwide; 73.24% of our young patients harbored EGFR or ALK mutations." (PMID 32967633, 2020). "Using ISET followed by FISH and IHC, CTCs can be a reliable source for the detection of ALK-gene rearrangements in lung cancer patients, with ≥90% concordance with the tissue biopsy." (PMID 37362555, 2020). "In a study using real-time PCR to assess ALK status in lung cancer, 33 ALK-positive and 28 ALK-negative patients, assessed by fluorescent in situ hybridization (FISH) break-apart, were enrolled." (PMID 33207619, 2020). "Crizotinib was approved by the FDA as a first-line treatment of ALK-rearranged nonsmall cell lung cancer (NSCLC) in 2011 and was approved in the United States and European Union for the therapy of patients with ROS1-positive advanced NSCLC in 2016." (PMID 33381185, 2020). "Saracatinib (AZD0530) targets Fyn and inhibits the growth of lung cancer cells that are resistant to ALK inhibitors, interestingly, this compound also suppresses Fyn induced invasion and metastasis by decreasing Vimentin and Snail." (PMID 32565740, 2020). "In this study, a proteomic analysis was useful for making inferences about the behavior of ALK-positive lung cancer cells in the early phase of ALC exposure." (PMID 31900393, 2020). "Lung cancer driver genes mainly include EGFR, ERBB2, MET, RET, ALK, and ROS1, all encoding genes for receptor tyrosine kinases (RTKs)." (PMID 33537237, 2020). "In this study, we show that inconsistent intersample ALK FISH results occur in about 5% of lung cancer patients." (PMID 32674491, 2020). "Aberrant changes in KRAS, EGFR, ALK have been recognized as key drivers of lung cancer, and are frequently identified in LUAD." (PMID 32855362, 2020). "Carcinogenic anaplastic lymphoma kinase (ALK) gene rearrangement occurs in approximately 5%–7% of non‐small cell lung cancer (NSCLC) patients." (PMID 32543087, 2020). "One of the first oncogenic drivers to be reported in lung cancer was the fusion of echinoderm microtubule-associated protein-like 4 (EML4) and anaplastic lymphoma kinase (ALK) (EML4-ALK) in 2007." (PMID 32640547, 2020). "In this study the combined effect of crizotinib and the MEK inhibitor selumetinib was investigated in both crizotinib naïve (H3122) and crizotinib resistant (CR-H3122) ALK-positive lung cancer cells." (PMID 31827192, 2019). "Mucinous cribriform pattern was a previously reported histologic feature as a fusion gene-associated feature, such as ALK, ROS1, and RET rearranged lung cancer." (PMID 31561631, 2019). "In lung cancer, AM exhibited a greater genetic heterogeneity of EGFR mutation and ALK rearrangement." (PMID 31703713, 2019). "ROS proto‐oncogene 1, receptor tyrosine kinase (ROS 1), and anaplastic lymphoma kinase (ALK) rearrangements are present in approximately 2% and 5% of non‐small cell lung cancers (NSCLCs), respectively." (PMID 31651105, 2019).
lung cancer (continued). "In lung cancer cancers, epidermal growth factor receptor (EGFR) mutation or anaplastic lymphoma kinase (ALK) fusion transcript status should be considered in conjunction with their intrinsic EMT process." (PMID 31341890, 2019). "Most non‐small cell lung cancer (NSCLC) patients relapse on anaplastic lymphoma kinase‐tyrosine kinase inhibitor (ALK‐TKI) therapy because of acquired resistance." (PMID 31338990, 2019). "It is also worth noting that LCAT1 was upregulated in a distinct subgroup of lung cancer patients that don’t have actionable mutations in EGFR, ALK, ROS or NRAS." (PMID 31779616, 2019). "Rapid developments in molecular biology provide the evidence that driver mutation, such as epidermal growth factor receptor (EGFR) and anaplastic lymphoma kinase (ALK) genes, play an important role in the oncogenesis of non–small cell lung cancer (NSCLC)." (PMID 30609789, 2019). "Although crizotinib has clear efficacy in patients with ALK-positive lung cancer with end-stage renal disease, the optimal dose of crizotinib should be identified in patients receiving regular hemodialysis." (PMID 31588629, 2019). "In this paper, an ALK‐positive advanced lung cancer patient with multiple organ metastases was successfully treated with salvage sublobar resection after multimodal treatments and obtained treatment‐free remission (TFR) for more than 3 years." (PMID 31285825, 2019). "Recently, ALK inhibitors have been used for the treatment of ALK-positive lung cancer, and their high clinical effect has also been demonstrated in cases of advanced stage lung cancer." (PMID 31030664, 2019). "We demonstrated that PCR-based target sequencing using a tiling primer set and two-step mapping/alignment quantitatively detected ALK fusions in cfDNA from lung cancer patients." (PMID 31513617, 2019). "This has led to FDA approved drugs for EGFR mutations, ALK rearrangements, ROS1 rearrangements, BRAF mutations, and NTRK rearrangements making up more than 20% of non‐small cell lung cancer patients." (PMID 31803961, 2019). "We encountered a case in which alectinib was administered as a primary treatment for ALK-positive lung cancer with brain metastases, but our patient died in a short period of approximately 4 months." (PMID 31030664, 2019). "Examples include erlotinib and crizotinib, which are specific for mutant EGFRs and ALK/ROS-driven lung cancers, respectively." (PMID 31601997, 2019). "In this study, we focused on the reliability of the detection of C-terminus ALK protein for the diagnosis of ALK fusion using various types of lung cancer cell lines and tissues." (PMID 30943926, 2019). "Through preclinical study, tenfold more potent than crizotinib inhibiting ALK-positive lung cancer cell lines was observed." (PMID 31023335, 2019). "Crizotinib was the first tyrosine kinase inhibitor (TKI) targeting ALK and demonstrated remarkable efficacy against ALK-positive lung cancer." (PMID 30866974, 2019). "ALK fusion-positive lung cancer comprises a small percentage of the NSCLC population with currently available therapeutic tyrosine kinase inhibitors, such as crizotinib." (PMID 30935143, 2019). "The novel ALK-translocated lung cancer cell lines together with their subclones will enable further understanding of the development of drug resistance within the heterogeneous tumour microenvironment." (PMID 30658414, 2019). "Tyrosine kinase inhibitors targeted to anaplastic lymphoma kinase (ALK) have been demonstrated to be effective for lung cancer patients with an ALK fusion gene." (PMID 31513617, 2019). "Anaplastic lymphoma kinase (ALK)-rearranged lung cancers are most often TTF-1 positive tumors, characterized by an acinar pattern with mucin/signet-ring cell morphology." (PMID 31330946, 2019).
lung cancer (continued). "Crizotinib and ceritinib have demonstrated superior efficacy to platinum‐based chemotherapy as front‐line treatment for patients with ALK‐positive advanced non‐small cell lung cancer (NSCLC)." (PMID 31613427, 2019). "Central nervous system (CNS) metastases from anaplastic lymphoma kinase (ALK)-positive lung cancer often results in failure of ALK-tyrosine kinase inhibitor (TKI) therapy." (PMID 31285826, 2019). "First, the EV-RNA signatures, low EV-miR-21-5p and high miR-486-3p, MEG3 and XIST identified in this study require clinical validation in a larger patient cohort to confirm their prognostic relevance in ALK-translocated lung cancer." (PMID 30658414, 2019). "EVs were isolated from conditioned medium (CM) of FA34 or from serum samples from patients with lung cancer and prescribed ALK-TKI treatment." (PMID 30658414, 2019). "In total, 80 cases were confirmed to be stage III or IV lung cancer patients that had received 1st line chemotherapy (19 were excluded because of EGFR/ALK positivity)." (PMID 31744064, 2019). "Genotyping studies revealing genetic alterations in the various subtypes of lung cancer accounting for tumorigenesis led to the development of targeted therapies, namely directed to EGFR, ALK, and KRAS mutated variants." (PMID 31795465, 2019). "ALK-positive lung cancer is a form of lung cancer that accounts for approximately 5% of non-small cell lung cancers." (PMID 31030664, 2019). "Next-generation TRK inhibitors can salvage resistance to a first-generation TRK inhibitor in select cases, a paradigm similar to that observed for ALK or ROS1 fusion-positive lung cancers." (PMID 31738426, 2019). "Clinical benefit of ALK tyrosine kinase inhibitors (ALK‐TKIs) in ALK‐rearranged lung cancer has been limited by the inevitable development of acquired resistance, and bypass‐molecular resistance mechanisms remain poorly understood." (PMID 31633304, 2019). "This is presumably due to the circumstance that most samples were early-stage, resected lung cancers; since it has been shown that ALK-rearrangements tend to occur more often in advanced, mainly stage IV, cancers." (PMID 30744199, 2019). "While chemotherapy has been shown to be effective in ALK-positive lung cancer patients, and remains a viable option in patients with ALK translocations, it has been reported that chemotherapy-only treatment was inferior to all ALK inhibitor subgroups." (PMID 30699985, 2019). "Other studies have also reported a high frequency of ALK fusions in young patients with lung cancer." (PMID 31387567, 2019). "In contrast, under sequential treatment with ALK TKI the median life expectancy of ALK+ lung cancer patients currently exceeds 5 years." (PMID 31139322, 2019). "In EGFR-mutant and ALK-rearranged lung cancers, early data on the decreased activity (compared with unselected cancers) of immunotherapy resulted in the exclusion of patients with these tumors in registration-enabling studies." (PMID 31192313, 2019). "Somatic mutations in the ALK gene have been identified in different cancers, including lung cancer, which has led to the development of ALK‐inhibitors for therapy." (PMID 31066027, 2019). "We found that compared to recurrence patients, Met, ALK, APC, PTEN, ERBB4, NF1, and other genes in recurrence-free patients never mutated, involving multiple tumor suppressor genes and lung cancer-driven genes." (PMID 31182981, 2019). "Crizotinib has demonstrated good efficacy in patients with anaplastic lymphoma kinase (ALK)‐positive non‐small cell lung cancer (NSCLC)." (PMID 31407528, 2019). "We added bevacizumab (15 mg/kg, every 3-4 weeks) to the regimen of four ALK-positive lung cancer patients with brain radiation necrosis who were receiving ALK-TKI therapy." (PMID 31285826, 2019). "Certain genes are tumor-type specific: EML4-ALK fusions have been detected in lung cancer samples, and nucleophosmin (NPM1)-ALK fusions were found in anaplastic large cell lymphoma (ALCL)." (PMID 31513617, 2019).
lung cancer (continued). "This underscores the utility of sequential TRK inhibitor use in select patients, a paradigm that parallels the use of targeted therapies in other oncogenic driver-positive cancers, such as ALK fusion-positive lung cancers." (PMID 31738426, 2019). "While some inhibitors are under investigation in clinical trials, others are now approved for treatment, notably in ALK-positive lung cancer." (PMID 30813562, 2019). "Based on this observation, he was diagnosed as having ALK-positive lung cancer with cerebral metastases, and administration of alectinib 600 mg/day was started from day 23 after admission." (PMID 31030664, 2019). "We investigated the combined effect of crizotinib with selumetinib in both crizotinib naïve and crizotinib resistant ALK-positive lung cancer cells." (PMID 31827192, 2019). "Recent study showed that pyroptosis was also involved in the response of target therapy in KRAS-, epidermal growth factor receptor (EGFR)—or anaplastic lymphoma kinase (ALK)-driven lung cancer." (PMID 31616642, 2019). "Our findings therefore add support to the clinical investigation of dual ALK/MEK inhibition therapy as a strategy to delay or overcome drug resistance in ALK-positive lung cancer, and points the way toward possible drug therapies with three or more targets." (PMID 31827192, 2019). "In the present study, we expanded the detection range to include mutations of 59 common cancer-associated genes and fusions of ALK and ROS1, and only a few classic lung cancer GA were observed." (PMID 31387567, 2019). "Rearrangement of ALK has been described in various tumors, mostly in lymphomas, lung carcinomas, and thyroid carcinomas." (PMID 31905821, 2019). "More remarkably, although ovarian metastasis from lung carcinoma has an extremely low incidence, ALK rearrangement in these patients has occasionally been reported." (PMID 31455365, 2019). "The identification of ALK rearrangements in lung cancer patients has sparked the development of a series of ALK TKI from different companies." (PMID 29495603, 2018). "Patients with Echinoderm microtubule-associated protein-like 4 (EML4)-anaplastic lymphoma kinase (ALK) positive lung cancer are sensitive to ALK-kinase inhibitors." (PMID 29304828, 2018). "A subset of lung cancers is dependent on the anaplastic lymphoma kinase (ALK) oncogene for survival, a mechanism that is exploited by the use of the ALK inhibitor crizotinib." (PMID 29507657, 2018). "We observed 73 patients with advanced ALK-positive lung cancer who underwent different treatment strategies, and 93.2% (68/73) of the patients received crizotinib treatment." (PMID 29298713, 2018). "As reported recently, ALK+ lung cancer cells demonstrate a dependence on MAPK signaling for growth and survival and as a mechanism of ALK inhibitor resistance." (PMID 29507657, 2018). "Small-molecule inhibitors of Anaplastic Lymphoma Kinase (ALK) approved in ALK fusion-positive lung cancer are currently undergoing clinical assessment in patients with ALK-mutant NB." (PMID 29642598, 2018). "As a TKI-relevant example, analysis of the degree of tumor shrinkage in response to ALK inhibitors in patients with EML4-ALK positive lung cancer revealed a highly significant positive correlation with overall and progression-free survival." (PMID 29458371, 2018). "The two main commercially available amplicon-based methods are the Ion AmpliSeq RNA Lung Cancer Research Fusion Panel (Thermo Fisher Scientific, Waltham, MA, USA) and the Archer® FusionPlex® ALK, RET, ROS1 v2 kit (ArcherDX, Boulder, CO, USA)." (PMID 29455675, 2018). "This vast knowledge base of the EM4L-ALK signaling network in lung cancer cells represents an invaluable resource for the identification of potential targets for ALK combination therapy." (PMID 29455675, 2018).